CCL20 (C-C motif chemokine ligand 20)
Diseases named in the same sentence as CCL20 in open-access papers (continued):
Sharing a sentence is not in itself a finding about the gene and the disease.
melanoma (continued). "Moreover, in future work, the dynamics of CCL20 should be investigated to further understand the role of this cytokine for melanoma patients undergoing ICI." (PMID 38730689, 2024). "In murine vaccine model systems analyzing protective or therapeutic efficacy against malaria, tuberculosis, and melanoma, we have studied the impact of fusing vaccine antigen to the chemokine macrophage inflammatory protein 3α (MIP-3α), also known as chemokine (C–C motif) ligand 20 (CCL20)." (PMID 38370404, 2024). "CCL20 may represent a novel blood biomarker for the prediction of prognosis in advanced melanoma under immunotherapy with a special emphasis on progression." (PMID 38730689, 2024). "To confirm this, we knocked down CCR6 expression in melanoma cells and examined whether the effect of CCL20 on CM development was attenuated or eliminated." (PMID 37182147, 2023). "Additionally, the interaction between CCR6 and CCL20, which plays a decisive role in melanoma pathogenesis beyond chemoattraction, is considered to be important for CM development." (PMID 37182147, 2023). "Besides, propionate and butyrate reduced the lung metastasis of melanoma cells by increasing the expression of chemokine (C-C motif) ligand 20 (CCL20) in lung endothelial cells and reducing the recruitment of Th17 cells." (PMID 36140990, 2022). "The ability of CCR6-expressing pDCs to migrate in response to CCL20 was demonstrated in transwell migration assays, suggesting that CCL20 produced in the TME might participate in recruiting CCR6-expressing pDCs in melanoma tumors." (PMID 36232698, 2022). "DNA vaccines containing a fusion of the gene encoding chemokine MIP-3α (CCL20), the ligand for CCR6 on immature dendritic cells (DCs), to melanoma-associated antigen genes have enhanced anti-tumor immunity and efficacy compared to those lacking the chemokine gene." (PMID 36741387, 2022). "Importantly, we showed that stromal CCL20 predicted poor survival in a cohort of 40 primary melanoma patients and identified TAMs as the main stromal source of CCL20 in melanoma tissues." (PMID 34439098, 2021). "Melanoma TAMs were also characterized in situ by their high content of CCL20, TNF, and VEGFA by multicolor immunofluorescence in cryopreserved samples; we now show that this particular cytokine profile may be detected and quantified in diagnostic FFPE." (PMID 34439098, 2021). "Stromal levels of CCL20 in primary melanomas may be a clinically useful marker for assessing patient risk, making treatment decisions, and planning or analyzing clinical trials." (PMID 31395078, 2019). "CXCR4 and CCL20 expression has been described in a variety of human neoplasms, including colorectal, lung, pancreatic and breast human adenocarcinomas, malignant glioma, leukemia, lymphoma and melanoma as well as by normal keratinocytes." (PMID 19340288, 2009). "In line with the previous report on CCL20, we observed that high serum CCL20 concentrations before therapy are associated with significantly impaired PFS (p = 0.0033) and significantly lower overall survival rates (p = 0.042) in this single-center advanced melanoma cohort." (PMID 38730689, 2024). "As the role of CCL20 in humans has only been demonstrated in tissue samples for melanoma in the past, we investigated whether CCL20 could also serve as a blood-based prognostic biomarker in melanoma patients." (PMID 38730689, 2024). "CCL20 expression has been described in a variety of human neoplasms, including colorectal, lung, pancreatic and breast human adenocarcinomas, malignant glioma, leukemia, lymphoma and melanoma However, the role of CCL20 in cancer development remains controversial." (PMID 19340288, 2009). "In skin cancers such as melanoma, pDCs are recruited to the TME via chemokine C-C motif ligand 20 (CCL20)." (PMID 40725022, 2025). "In conclusion, CCL20 is a promising blood-based biomarker for therapeutic response and ICI in advanced melanoma." (PMID 38730689, 2024).
melanoma (continued). "Overexpression of GLI1 in A375 melanoma cells drastically downregulated CCL7, CCL2, CCL20 and CXCL8 mRNA level." (PMID 39090759, 2024). "Cytokine array from SSM2c cells transduced with LV-c or LV-shGLI1 showed a significantly higher secretion of CCL7, CCL2, CCL20 and CXCL8 (IL-8) in CM collected from GLI1-silenced melanoma cells." (PMID 39090759, 2024). "Marked downregulation of expression of TREM1 and known TREM1 target genes (NFKB1, CCL20, IL6, and CXCL8) was determined in melanoma PDX models treated with VJDT." (PMID 37651197, 2023). "The distant effect of SCFAs promotes the expression of CCL20 (also known as LARC or MIP3A) in lung endothelial cells, which in turn recruits Th17 cells that attenuate melanoma cell metastasis in the lung." (PMID 35682816, 2022). "Taken together, melanoma cells secreted a variety of proinflammatory factors, mainly cytokines, such as IL-1β and IL-8, and chemokines, such as CXCL10, CXCL11, and CCL20, during CIS, while during TIS, melanoma cells produced lower levels of SASP proteins." (PMID 35563820, 2022). "First, we established conditions to quantify by multicolor fluorescent-microscopy the content of CCL20, TNF, and VEGFA in CD68+ cells in FFPE melanoma tissues." (PMID 34439098, 2021). "We previously identified co-expression of CCL20, TNF, and VEGFA cytokines by tissue TAMs in an exploratory set of 7 metastasizing melanomas." (PMID 34439098, 2021). "Melanoma cells, which upregulate CCR6, are able to establish a paracrine loop between themselves and CCL20-expressing TAMs, promoting tumour growth and survival, likely in part due to TAMs promoting protumour immune cell infiltration." (PMID 34830780, 2021). "Some of these genes had already been described in earlier studies as being down-regulated during melanoma progression: COL17A1, DSC3, KLK7, SLPI and KLK8, or over-expressed, e.g. CCL20, THBS1 and THBS4." (PMID 22032772, 2011). "Furthermore, these PDCs migrated toward CCL20 and could be found in melanoma lesions." (PMID 20976171, 2010). "In univariable regression, sex, age group, AJCC stage, primary melanoma site, baseline therapy and elevated LDH levels at baseline did not significantly impact PFS, whereas ECOG, CCL20 group and elevated S100 at baseline increased the risk of an impaired PFS." (PMID 38730689, 2024). "With respect to OS, we observed that melanoma patients with high CCL20 levels have shorter survival times compared to patients with low CCL20 levels (median OS not reached in the low-CCL20 group) (p = 0.042)." (PMID 38730689, 2024). "The migration of pDCs to the TME could be directed through the CCL20/CCR6 axis, as proposed in melanoma patients." (PMID 36232698, 2022). "We previously showed that both pro-inflammatory (GM-CSF) and anti-inflammatory (M-CSF) human macrophages (MP-GM and MP-M, respectively) co-cultured with melanoma metastatic cell lines (BLM and A375), displayed a distinctive CCL20 mRNA up-regulation and secreted large amounts of CCL20 protein." (PMID 34439098, 2021). "However, there were differences in the cytokine profile up-regulated regarding the MP polarization profile; MP-GM/melanoma produced more TNF and CCL20, whereas MP-M/melanoma produced more VEGFA." (PMID 34439098, 2021). "Circulating pDCs from patients with melanoma have been found to express higher amounts of CCR6 and CXCR4, while their corresponding ligands CCL20 and CXCL12 are expressed on melanoma cells, suggesting that the CCR6/CCL20 and CXCR4/CXCL12 axes promote pDC migration from blood to melanoma foci." (PMID 29085361, 2017). "As the analysis of serum C-C motif chemokine ligand 20 (CCL20) is not standard in clinical practice, and, therefore, no reference range exists, we determined the median CCL20 levels of the 101 advanced melanoma patients at baseline prior to the initiation of immunotherapy." (PMID 38730689, 2024).
melanoma (continued). "Thus, we determined the expression of known NF-κB targets in melanoma, e.g., MMP9, CCL20 and IL1B." (PMID 32712598, 2020). "In addition, our study allows the identification of an immunosuppressive signature characterized by high GLI and low cytokine/chemokine expression (CCL7, CCL2, CCL20, CXCL8, CXCL1 and CXCL10), which could be used to stratify melanoma patients with poor survival." (PMID 39090759, 2024). "B16 melanoma, engineered to overexpress CCL20, grew slowly in CCR6 knockout mice compared to WT mice, with fewer leukocytes that infiltrated into the melanoma in the absence of CCR6." (PMID 38786066, 2024). "Significantly, higher contents of the intracellular cytokines CCL20, TNF, and VEGFA were quantified in TAMs infiltrating metastasizing compared to non-metastasizing skin primary melanomas (p < 0.001)." (PMID 34439098, 2021). "Melanoma BLM cells were also analyzed after co-culture, showing no expression of CCL20 and low induction of TNF mRNA, whereas VEGFA mRNA was basally expressed by BLM cells." (PMID 34439098, 2021). "We previously reported that in human melanoma the chemokine axis CCR6/CCL20 is involved in a cooperative paracrine loop between CCR6 expressing tumor cells and CCL20 secreted by nontumoral cells in the stroma." (PMID 34439098, 2021).
pancreatic cancer (43 papers, 2009 to 2025). "At the transcript level, mRNA expression of Ccl2, Ccl7, Cxcl1, Cxcl3, and Csf2 was markedly downregulated in Ccn1‐deficient pancreatic tumors, whereas Cxcl5, Csf1, and Csf3 expression remained unchanged, and Ccl20 mRNA was elevated." (PMID 40287974, 2025). "The CCL20/CCR6 system has been demonstrated within pancreatic cancer cell lines and PCA-associated tissues." (PMID 30004409, 2018). "Another study reported that high expression of VDR in pancreatic cancer promotes M2 macrophage polarization and recruitment through the secretion of CCL20, which activates tumor progression." (PMID 40453717, 2025). "CC-chemokine receptor 6 (CCR6) acts as a receptor for CCL20 in pancreatic cancer cells, mediating the promotion of pancreatic cancer growth and liver metastasis by CCL20 in a mouse model." (PMID 40034694, 2025). "CC-chemokine ligand 20 (CCL20) expression is abnormally elevated in TAMs of pancreatic cancer tissues." (PMID 40034694, 2025). "CCL20 activated by vitamin D receptor in pancreatic cancer cells enhanced tumor progression through CCL20-mediated macrophage recruitment and polarization toward M2 phenotype." (PMID 39985603, 2025). "Macrophage proinflammatory chemokine-3α (MIP-3/CCL20) is overexpressed in pancreatic carcinoma cells and infiltrates macrophages near tumors." (PMID 37373025, 2023). "Pancreatic cancer cells acquire TRAIL resistance through not only autocrine CCL20 but also paracrine recruitment of immune cells." (PMID 32707869, 2020). "Using ELISA, we asked if pancreatic cancer cells produced the predominant mucosal DC-specific chemokine CCL20." (PMID 31036082, 2019). "Recent studies have identified matrix metalloproteinase production to up-regulate CCL20, which promotes pancreatic tumor cell movement and their metastatic invasion." (PMID 30004409, 2018). "It was previously showed that both pancreatic cancer cells and tumor-associated macrophages are in vivo sources of CCL20 mRNA, and CRC cell lines expressed transcripts for both CCL20 and its receptor CCR6." (PMID 24979261, 2014). "The results of this manuscript show that CCL20 and its corresponding receptor CCR6 are significantly up-regulated in patients with pancreatic cancer (PCA) and that CCL20 is significantly associated with advanced T-category in those patients." (PMID 20459729, 2010). "In PCA tissues the CCL20 transcript was detected in moderate to high levels and expression of the CCL20 protein was observed in cancer cells within the pancreatic tumor mass." (PMID 20459729, 2010). "However, chemokine CCL20 is upregulated in patients with pancreatic cancer and related to advanced T categories, and high expression of CXCL5 is associated with shorter OS in hepatocellular and cholangiocarcinoma." (PMID 37779898, 2023). "However, the role of CCL20-stimulated M2 and complement-stimulated M1 remain unreported in pancreatic cancer, a comprehensive consideration in the context of senescence is also missing." (PMID 37398643, 2023). "Similar effects of CCL20 on cancer cells are also displayed in pancreatic cancer." (PMID 35864953, 2022). "Additionally, IL‐4‐treated M2‐type macrophages highly express CCL20 and the CCL20/CCR6 axis promotes pancreatic cancer proliferation and distant metastasis via inducing epithelial–mesenchymal transition (EMT) in vivo." (PMID 35702353, 2022). "Moreover, pancreatic cancer cells secrete IL‐11 and CCL20 in response to NTS stimulation, which in turn evoke inflammatory responses in the tumor microenvironments." (PMID 33034134, 2021). "CCL20 was highly expressed in several cancer types such as colorectal malignancies, metastatic triple-negative breast cancer, non-small-cell-lung-cancer, hepatic malignancies and pancreatic carcinoma." (PMID 27723802, 2016). "Also CCL20 is up-regulated in pancreatic cancer and overexpression of CCL20 in prostate cancer cells promotes tumor growth and invasiveness." (PMID 23800251, 2013).
pancreatic cancer (continued). "To speculate, the CCR6 high PDCs in our system might migrate into the CCL20 positive pancreatic tumor microenvironment." (PMID 20976171, 2010). "Recent studies demonstrated that CCL20 may promote pancreatic tumor cell migration and invasion through the up-regulation of matrix metalloproteinase production." (PMID 20459729, 2010). "Doses of at least 4 Gy induced module 1 (e.g., CCL5, CXCL10) and module 4 (e.g., CCL20, CXCL8) chemokines in pancreatic cancer cells, with larger effects using higher radiation doses." (PMID 40811032, 2025). "Accordingly, we showed in pancreatic cancer cells (KPC) in vitro an induction of monocyte/macrophage-chemoattractant cytokines such as CCL2/MCP1, CCL20/MIP3α, CXCL2/MIP2α and also GM-CSF by Juzentaihoto (and the combination)." (PMID 39723364, 2024). "GABRP has been reported to play an immunomodulatory role in pancreatic cancer in a neurotransmitter independent manner, promoting macrophage infiltration by inducing the expression of CXCL5 and CCL20, and thereby affecting tumor growth and metastasis." (PMID 34957220, 2021). "The addition of recombinant CCL20 has enhanced EMT by increasing the expression of p-AKT, p-ERK, and N-cadherin and decreasing the expression of E-cadherin in pancreatic cancer cell lines." (PMID 32707869, 2020). "CCR6 is also the receptor for the chemokine CCL20 which is produced by M2 macrophage, and mediates the effect of CCL20 on EMT and cell invasion of pancreatic cancer cells." (PMID 30925924, 2019). "CCL-20 (or macrophage pro-inflammatory chemokine-3α, MIP-3α), a C-C motif chemokine, is overexpressed in pancreatic carcinoma cells and stimulates growth of tumor cells." (PMID 24260500, 2013). "Moreover, IL4-stimulated M2-type macrophages strongly express CCL20 and promote epithelial-mesenchymal transition (EMT) and pancreatic cancer cell invasion." (PMID 32707869, 2020). "Moreover, expression of the CCL20/CCR6 system has been reported in PCA tissues and pancreatic cancer cell lines." (PMID 20459729, 2010).
rheumatoid arthritis (39 papers, 2008 to 2026). A chronic, systemic autoimmune disorder characterized by inflammation in the synovial membranes and articular surfaces. "Patients with rheumatoid arthritis were found to have a greater risk of depression than normal controls and patients with remitted vasculitis, and CCL20 (Th17) was reported to be significantly upregulated in active vasculitis patients." (PMID 33971621, 2021). "These genes are involved in immune system regulation, some of which are associated with the host response to rheumatoid arthritis (CCL20, IL1A, and MMP1)." (PMID 33301474, 2020). "Infliximab depresses TNF-induced CCL20 upregulation via the nuclear factor kappa B (NF-kB) pathway in synoviocytes which causes rheumatoid arthritis." (PMID 30453514, 2018). "CCL2 and CCL20 are chemokines implicated in rheumatoid arthritis synovitis and are produced by OA synovium in the presence of pro-inflammatory cytokines." (PMID 20799933, 2010). "In humans, CCR6 and/or MIP-3α/CCL20 have been implicated in the pathogenesis of rheumatoid arthritis and inflammatory bowel disease, autoimmune disorders in which Th17 cells are thought to play a crucial role." (PMID 23283206, 2009). "Moreover, we again confirmed the downregulation of the expression levels of rheumatoid arthritis-associated genes, including IL-6, CCL20, and CCL5 using the RT-PCR analysis." (PMID 37777063, 2024). "In rheumatoid arthritis, CCL-20 expression correlated to bone loss and patient survival." (PMID 34831397, 2021). "Around 3% of circulatory monocytes expressed CCR6 in blood and synovial fluid from rheumatoid arthritis patients and these monocytes responded to CCL20 chemotaxis in vitro." (PMID 33679793, 2021). "More recent evidence has demonstrated increased levels of CXCL8, CXCL9, CXCL10, and CCL20 in rheumatoid arthritis, indicating the importance of chemokines in inflammatory bone diseases." (PMID 33510341, 2021). "CCL20, a member of the C-C motif chemokine subfamily, participates in many diseases’ progression—including rheumatoid arthritis (RA), psoriasis, and immune response—and promotes the malignancy in colorectal cancer and lung cancer." (PMID 30052635, 2018). "In our study, a significant proportion of genes elevated by IL-1B and IL-36 belonged to the KEGG rheumatoid arthritis pathway (e.g., CCL20, CXCL7, and CXCL1)." (PMID 29434599, 2018). "Increased levels of CCL20 are expressed in subchondral bone tissues of rheumatoid arthritis patients." (PMID 27822475, 2016). "In vivo, a chemotactic effect of the CCL20/CCR6 axis has been demonstrated in diseases such as rheumatoid arthritis and autoimmune encephalitis." (PMID 24699535, 2014). "Although CCL20 has been implicated in several autoimmune diseases, such as rheumatoid arthritis (RA) and Experimental Autoimmune Encephalomyelitis (EAE), little is known about the association of CCL20 with GD and its regulatory factors." (PMID 23717583, 2013). "JNK pathway is also involved in CCL-20 production in keratinocytes and Rheumatoid arthritis synoviocytes after inflammatory stimuli." (PMID 24040124, 2013). "Interestingly, recent studies suggest that the therapeutic efficacy of anti-tumor necrosis factor-α therapies may result from the inhibition of CCL20 in rheumatoid arthritis synovium as this chemokine mediates key pathogenic events such as the recruitment of Th17 cells to the inflamed joints." (PMID 21961038, 2011). "CCL20 is also expressed in inflamed epithelial cells and in the synovial tissues of rheumatoid arthritis patients, while up-regulation of CCL20 along with other cytokines has been observed in human subjects one day after severe traumatic brain injury." (PMID 22040257, 2011). "Chemokines such as IL-8, CCL2 and CCL20 are produced by OA synoviocytes, but to a lower extent than rheumatoid arthritis cells." (PMID 20799933, 2010).